IL15 (interleukin 15)
Diseases named in the same sentence as IL15 in open-access papers (continued):
Sharing a sentence is not in itself a finding about the gene and the disease.
infection (continued). "That finding paralleled lower neutrophil counts in the peritoneal cavity of IL-15 SA-treated mice after infection." (PMID 26859674, 2016). "Another study showed that a highly virulent H5N1 virus induced antiviral (IFN-α and IFN-β) and proinflammatory (IL-4, IL-6, IL-8, and IL-15) cytokine mRNA expression in the lung at 24 h post infection, which abruptly decreased within the next 8 h." (PMID 27078641, 2016). "Wound infection lead to a significant decline in the blood neutrophil counts both in the vehicle- and IL-15 SA-treated groups at day 2 post infection." (PMID 26859674, 2016). "IL-15 SA treatment accentuated the CD4+ T cell activation more so than the CD8+ T cell activation in the liver after infection." (PMID 26859674, 2016). "This revealed 13 mediators of inflammation that correlated with infection status, which were, in order of strength of significance, IL-4, IL-5, IL-7, IL-15, IFN-α, IL-12, IFN-γ, IL-17, IL-1Ra, TNF-α, IL-1β, IL-10, and IL-2." (PMID 27418744, 2016). "One direct signal at the site of infection is production of IL-15, which directly triggers M1 MΦ differentiation." (PMID 27532668, 2016). "The levels of anti-inflammatory cytokine IL-10 were also significantly increased after infection and were amplified by IL-15 SA treatment." (PMID 26859674, 2016). "Intraperitoneal infection of mice with E. muris resulted in the production of IL-15, IL-12, and IFN-γ as well as an expansion of activated NKG2D+ NK cells." (PMID 27092553, 2016). "Infection increased the percentage of intraperitoneal neutrophils (Ly6G+F4/80-) in vehicle and IL-15SA-treated mice, but IL-15 SA treatment attenuated neutrophil recruitment at the site of bacterial inoculation." (PMID 26859674, 2016). "Both our study and theirs showed the ability of IL-15 SA to expand lymphocyte populations and to augment cytokine production during infection." (PMID 26859674, 2016). "It has been shown that inflammatory monocytes activate both NK cells and memory CD8+ T cells through producing IL-18 and IL-15 during infection." (PMID 26468944, 2015). "The splenic results agree with an earlier report showing significantly increased IFNγ levels in the serum and increased CD8+ T cells expressing IFNγ in IL-15 Tg mice after infection with mycobacterium bovis bacillus Calmette-Guérin." (PMID 26600079, 2015). "Among numerous cytokines modulating natural killer (NK) cell function, interleukin 15 (IL-15) exerts a broad range of effect from development and homeostasis, to activation of mature NK cells during infection." (PMID 26257729, 2015). "Following the data obtained for NK cells, also we observed significantly decreased expression levels of IL-15 in Fas- and FasL-deficient mice at 3rd, 7th, and 10th days of ECTV infection." (PMID 25873756, 2015). "In a separate study, IL-6, TNFα, IL-8, and IL-15 were significantly higher in the group with severe pH1N1 infection when a panel of nine serum cytokines was analyzed." (PMID 25003343, 2014). "A two-fold increase in IL-15 and ten-fold increase in IL-15Rα mRNA levels were observed 24 h and 48 h, respectively, after HTNV-infection, and IL-15 and IL-15Rα mRNA levels remained at elevated levels until at least 96 h post infection." (PMID 25412359, 2014). "In order to evaluate the role of antiviral innate immunity following SHIVSF162P4cy infection, the production of cytokines (IL-10, IFNγ, IL-15) and α-defensins were determined in plasma of infected monkeys." (PMID 24695530, 2014). "Serum proinflammatory cytokines were similar in both age groups, whereas significantly lower levels of IL-1beta, IL-18, IL-6, IL-12 and IL-15 were detected in the lungs of SARS-CoV-infected aged monkeys at either 5 or 10 days post infection." (PMID 24642138, 2014). "Of note, the acute phase of SIVagm infection resulted in significant increases of early cytokines, including IL-15, IP-10 and MCP-1, similar to pathogenic infection." (PMID 24991927, 2014).
infection (continued). "Strikingly, HTNV-infection was found to up-regulate the expression of IL-15 and IL-15Rα mRNA in both endothelial and epithelial cells." (PMID 25412359, 2014). "Perhaps, during multi-strain infection type I interferons or cytokines such as IL-12 and IL-15 are maintained at higher levels in response to the continued presence of m157Ly49H− strains of MCMV." (PMID 23300458, 2013). "Infection of Calu-3 cells with either virus induced HRV-associated increases in FGF-Basic, IL-15, IL-6, IL-28A, ENA-78 and IP-10." (PMID 23799120, 2013). "Ashkar and Rosenthal (2003) showed that IL-15 (−/−) mice, which lack NK and NKT cells, were more susceptible to infection." (PMID 23922974, 2013). "Blocking IL-15 delays NK cell entry to the site of infection and results in a disregulated control of early viral replication." (PMID 22624047, 2012). "In the lung parenchyma of control-treated animals, NK cells also accumulated over time post infection, similar to those in the lung airways, but the frequencies of NK cells in this site remained unchanged in IL-15-blocked mice." (PMID 22624047, 2012). "IL-15 production by RV infected macrophages was inversely related to lower respiratory symptom severity on subsequent RV16 experimental infection in the same subjects in vivo (r = −0.6, p = 0.022)." (PMID 21779162, 2011). "During the early phase of infection (day 1 until day 4) the absolute number of NK cells per spleen remained unaltered in both WT and IL-15−/− mice compared with the respective uninfected control mice." (PMID 20213736, 2010). "To this end we analysed the L. infantum-induced expression of IFN-γ in highly purified NK cells from uninfected congenic CD45.1+ WT donor mice that had been transferred into L. infantum-infected WT or IL-15−/− recipient mice 2 to 4 h after infection." (PMID 20213736, 2010). "Among interleukins, IL-18 and the IL-18 binding protein played a prominent role early in the course of infection, while later IL-15 became increasingly up regulated." (PMID 19583830, 2009). "Observations aboveclearly suggest that further examinations are needed to explain an actual role of IL-15 in immune and inflammatory response during infection controlby B burgdorferi." (PMID 16864901, 2006). "IL15 secretion was detectable in the supernatant starting from day 2 post-infection." (PMID 40474210, 2025). "In addition to memory response to infection, the simultaneous stimulation of NK cells with IL-12, IL-15, and IL-18 can lead to the generation of cytokine-induced memory-like (CIML) NK cells." (PMID 39066359, 2024). "Thus, Il15-/- mice are the most appropriate tool available to determine if there are NK cell-independent effects of IFNε on infection and protective responses." (PMID 38263527, 2024). "In brief, CAR T cell manufacturing included depletion of CD14+ and CD25+ cells, CD3/28 bead stimulation, transduction with lentivirus at multiplicity of infection of 0.3, removal of beads at day 7–9, followed by expansion for a total of 12–17 days in interleukin (IL)-2 and IL-15 cytokines." (PMID 38867077, 2024). "Due to the importance of IL-15 in NK cell development, Il15-/- mice are completely deficient in mature NK cells and thus, we do not detect NK cells in their FRTs during infection (Fig. EV5D)." (PMID 38263527, 2024). "Conversely to the promise of IL-15 as an LRA, the pro-survival effects have been implicated in sustaining persistent HIV infection by enhancing susceptibility of CD4+ T cells to infection in a SAMHD1-dependent manner, as well as promoting proliferation of CD4+CCR5+ T cells." (PMID 39401241, 2024). "Thus, restoring IL-15 increases the numbers of inactive, but has little effect on CD69+ NK cells during infection in Ifne-/- mice, indicating that IFNε and its IL-15-independent effects are required for local activation." (PMID 38263527, 2024).
infection (continued). "Thirteen of the tested proteins (G-CSF, GM-CSF, M-CSF, TNF-β, IFN-gamma, TNF-α, IL-1 β, IL-3, IL-6, IL-7, IL-15, IL-17, IL-19) were found in the hemolymph and hemocytes of G. mellonella; however, the results regarding the influence of infection differed according to the detection method." (PMID 38774871, 2024). "Arming oHSV-1 through the insertion of proinflammatory cytokines, including granulocyte–macrophage colony-stimulating factor (GM-CSF), IL-12, and IL-15, has improved its antitumor efficacy, and lacZ insertion has allowed for tracking viral distribution and infection." (PMID 39066359, 2024). "Similarly, IL-15 protein levels are reduced (~25%) in uterine lavage from Ifne-/- compared to WT mice, particularly during infection (p < 0.05)." (PMID 38263527, 2024). "In addition, IL-15 can promote the survival of IECs during infection and inflammation; however, overexpression on basolateral surfaces can induce apoptosis and T-cell activation leading to disease, depending on the stimulus." (PMID 39392674, 2024). "We next determined if restoring IL-15 levels in Ifne-/- mice could restore protective NK cell responses during infection." (PMID 38263527, 2024). "Suggesting that Ec-IL15Rα may play roles in enhancing the binding and assisting Ec-IL15, to co-express and operate together against pathogen infection." (PMID 38066992, 2023). "We therefore conclude that the Hu-NSG-Tg(IL-15) mouse model fulfills an unmet need and provides a valuable in vivo resource for the study of NK cell responses and therapeutic applications to control, eradicate, or prevent infection with HIV-1." (PMID 36851579, 2023). "So the modest effect seen on CD8+ T and NK cells of additional exogen IL-15 administration during untreated infection could be due to already high levels of endogen IL-1578 as well as short half-life of responder cells." (PMID 37767312, 2023). "We also found two cytokines down-regulated, a pro-inflammatory il15 gene, which promotes Th1 responses and T-cell maturation, and il10, an anti-inflammatory gene that is expressed under infection with stimulatory and inhibitory activities on several immune cells." (PMID 37422657, 2023). "Granzyme C upregulation after IL-15 stimulation suggests that granzyme C expression might serve as a surrogate to identify cells receiving IL-15 during homeostasis, infection, and inflammation." (PMID 37809077, 2023). "IL-15 has also presented higher concentration during microorganisms’ infection and may have an important role in innate and adaptative response at testicular site." (PMID 37033490, 2023). "IL‐15 treatment prior to infection could partially restore the deficiency of IFNAR1‐KO GMPs, indicating the importance of I‐IFN induction of IL‐15 production in myeloid cells." (PMID 37635627, 2023). "We then investigated whether IL-15 stimulation has an impact on infection and latency establishment of HIV-GKO bearing a CCR5-tropic envelope (R5 HIV-GKO)." (PMID 35499323, 2022). "Also after IL-15 stimulation, naive CD4+ T cells were the most resistant to HIV infection, with an average infection of 1.2%, while TEM cells were the most susceptible, with an average infection of 16.8%." (PMID 35499323, 2022). "Indeed, recently, the potential use of microglia engineered to express IL-15 upon infection with a recombinant AAV serotype 2 (rAAV2) carrying IL-15 (rAAV2-IL-15) was explored to counteract GBM growth in mouse models." (PMID 35681612, 2022). "The increase in productive infection suggested that IL-15 could also have a role in HIV transcription." (PMID 35499323, 2022). "When we calculated the percentage of productively and latently infected cells over total infection, we found that IL-15 stimulation minimally increased the percentage of productively infected cells while decreasing the percentage of latently infected cells compared to IL-2 stimulation." (PMID 35499323, 2022).
infection (continued). "Similarly, IL-15 levels were increased ~two-fold upon HCoV-OC43 infection in wild-type cells, while remaining unchanged in GR1−/− and G+/−GR1−/− cell lines." (PMID 35897807, 2022). "In the serum samples after infection, the increased inflammatory cytokines were IL-8 and IL-15." (PMID 33895780, 2021). "Infection with NTS serovars is known to stimulate an enhanced Th1-type bias by CD4+ or CD8+ T cells associated with increased production of proinflammatory cytokines IFN-γ, IL-18, IL-12, IL-15, and TNF-α." (PMID 33956909, 2021). "Indeed, administration of both bacteria, either alone or in combination, reduced significantly the expression of IL-15, while downregulation of IL-17 was detected uniquely after infection with C. jejuni." (PMID 33477806, 2021). "IL15, a natural killer cell activator cytokine, was significantly upregulated at 1 and 2 dpi while expression patterns of other proinflammatory cytokines varied between animals and days of infection." (PMID 34029358, 2021). "Higher levels of IL-15 and IL-21 in the local environment during SIVagm infection as compared to SIVmac infection might allow NK cell terminal differentiation." (PMID 33627642, 2021). "We then assessed the transcriptional profiles of pro-inflammatory cytokines Interleukin-6 (IL-6) and interleukin-15 (IL-15) and anti-inflammatory interleukin-10 (IL-10) under normal or iron-depleted conditions and determined how these were affected by infection." (PMID 34571900, 2021). "Differential gene expression in implanted CT26 tumors treated with mVG161 compared to equivalent tumors injected with VG160 revealed that infection with mVG161 bearing IL-12, IL-15, and IL-15RA transgenes powerfully stimulates a prototypical Th1 immune response (e.g., IFN-γ, TNF, and IL18)." (PMID 33182232, 2020). "To test whether production of IL-15 during infection was leading to the observed increase in SRC in TVM cells, we administered an IL-15 neutralising monoclonal antibody (mAb) to young mice infected with IAV." (PMID 32504069, 2020). "A hypothetical hybrid interactome of PSPs revealed that T. rangeli could enhance the production of IL-15, leading to NF-kB complex activation, and ultimately an immune response, which could explain the inability of T. rangeli to establish human infection." (PMID 32973747, 2020). "Notably, the NK cell-activating cytokines, IFNα, IL-12, and IL-15, were also elevated during the acute phase of the infection." (PMID 31467285, 2019). "Dam 4 exhibited an increase above baseline in IL-1β, IL-2, IL-6, IL-7, IL-15 and IL-16, and similar to Dam 2, peak levels of these cytokines were on day 14 post-infection with the exception of IL-15 (day 7); by 21 dpi, most cytokines had returned to baseline or were lower than peak levels." (PMID 30657788, 2019). "PRR pathways can induce high levels of IL-15 during infection." (PMID 29632538, 2018). "These discrepancies could be attributed to the fact that IL-15 peaks very fast after infection and then sharply decays." (PMID 29342870, 2018). "Increased infection risk at higher doses of tofacitinib could also be driven by JAK3 inhibition and subsequent downstream blockade of IL-15 survival signaling in NK cells." (PMID 30886973, 2018). "Seasonal H3N2 virus exposure, through vaccination or infection, can induce memory B cells that bind to the conserved stalk region of HAs.In vitro recall responses to these stalk-reactive antibodies can be enhanced by IL-15." (PMID 29479423, 2017). "IL-7 or IL-15 may also contribute to a qualitatively or quantitatively different cytokine milieu during the infection with M. tuberculosis, and signaling by both IL-7 and IL-15 synergizes to promote the generation of memory T cells responses." (PMID 28448542, 2017). "Both cell types can be infected with FV, but whether productive infection is required for IL-15 induction remains elusive." (PMID 28904191, 2017).
infection (continued). "This may be due to the higher plasma chemokine concentrations in the IL-15 SA-treated group, which can wash out plasma to tissue chemokine gradients and result in impaired mobilization of neutrophils to sites of infection." (PMID 26859674, 2016). "Furthermore, YopM from different Yersinia strains reduced the production of proinflammatory cytokines (i.e. Interferon–γ (IFN-γ), Interleukin-1β (IL-1β), Tumor Necrosis Factor-α (TNF-α), Interleukin-15 (IL-15)) in mice at 1–4 days post infection." (PMID 27300509, 2016). "Treatment with IL-15 SA further augmented cytokine production in this acute infection model." (PMID 26859674, 2016). "However, all lymphocyte populations in spleen and liver tissue declined markedly after infection in IL-15 SA-treated mice and were only marginally greater than in vehicle-treated infected mice." (PMID 26859674, 2016). "In some experiments, IL-15 SA was administered after burn injury, but before infection." (PMID 26859674, 2016). "In accordance with previous findings, significant decreases in hepatic HBV DNA and HBV RNA levels were obtained upon infection with AAV-expressed IL-15 or IFN-α alone, indicating an attenuation of HBV transcriptional activity and an abrogation of viral replication." (PMID 27440883, 2016). "As LCMV has been shown to infect BM stromal fibroblast and endothelial cells, it could well be that the cellular sources of IL-7 and IL-15 in the BM are severely affected by the infection." (PMID 26793197, 2015). "Moreover, IL-15 and lysozyme are secreted by macrophages and recruited to sites of infection to clear pathogens." (PMID 26572495, 2015). "Ectromelia virus (ECTV) infection of Fas- and FasL-deficient mice led to increased virus titers in lungs and decreased migration of IFN-γ expressing NK cells, CD4+ T cells, CD8+ T cells, and decreased IL-15 expression." (PMID 25873756, 2015). "The severe infection group had a significantly higher level of IL-15 than the control group." (PMID 24646014, 2014). "Interestingly, infection of IL-15 KO mice with the protozoan parasite Toxoplasma gondii or IL-15 KO, IL-15Rα KO, and RAG2/IL-2Rγ KO mice with MCMV infection results in rapid expansion of NK cells." (PMID 25197644, 2014). "Therefore, IL-15 in the uterus appears to play a more important role in NK cell recruitment but less of a role in early NK cell control of infection." (PMID 25197644, 2014). "Expression levels of interleukin (IL)-4, IL-10, IL-13 and tumor necrosis factor (TNF)-α were significantly up-regulated while interferon (IFN)-α, IFN-β, IFN-γ, IL-1β,IL-2, IL-3, IL-15, IL-17F, IL-18 and colony-stimulating factor (CSF)-1 were markedly decreased in PBMCs at all stages of infection." (PMID 24358317, 2013). "As NK cells have to be primed by IL-15 to respond to T. cruzi, the source of this cytokine in vivo during infection may be questioned." (PMID 23819002, 2013). "Not only might there be different cellular sources of IL-15 at different times after infection, but IL-15 signaling in NK cells could also be regulated by the context in which IL-15 is presented." (PMID 22624047, 2012). "IL-7 and IL-15 were detected previously after MVA infection of HeLa cells." (PMID 21625608, 2011). "We first checked the secretion of IL-12 by splenic mDC of WT and IL-15−/− mice following infection." (PMID 20213736, 2010). "IL-15 promotes CD8 T cells homeostatic proliferation in response to infection." (PMID 20003352, 2009). "In agreement with our data, it has been reported that IL-15 is over-produced systemically during infections and inflammatory diseases, and we hypothesize that the systemic expression of IL-15 may contribute to the activation and migration of circulating CD8+ T cells." (PMID 38709823, 2024).